PLOD2 (procollagen-lysine,2-oxoglutarate 5-dioxygenase 2)
Description:
Forms hydroxylysine residues in -Xaa-Lys-Gly-sequences in collagens. These hydroxylysines serve as sites of attachment for carbohydrate units and are essential for the stability of the intermolecular collagen cross-links.
Synonyms: LH2; TLH; BRKS2
Tractability: Antibody: UniProt places it where antibodies can reach, with medium confidence; UniProt predicts a signal peptide or a membrane-spanning region; its Gene Ontology location is reachable by antibodies, with medium confidence. PROTAC: ubiquitination databases record sites on it; its protein half-life has been measured; a small molecule that binds it is known.
Target class: Enzyme; Oxidoreductase
Gene: Protein-coding gene on chromosome 3 (146,035,139 to 146,163,725, reverse strand). Ensembl gene ENSG00000152952.
Subcellular location: Rough endoplasmic reticulum membrane; Cytoplasm
Subcellular location (Human Protein Atlas): Cytosol; Nucleoli
Pathways (Reactome):
Extracellular matrix organization: Collagen biosynthesis and modifying enzymes
Gene Ontology:
Molecular function: procollagen glucosyltransferase activity; procollagen-lysine 5-dioxygenase activity; iron ion binding; L-ascorbic acid binding; oxidoreductase activity, acting on paired donors, with incorporation or reduction of molecular oxygen
Biological process: collagen biosynthetic process; protein O-linked glycosylation; response to hypoxia; collagen fibril organization
Cellular component: cytoplasm; extracellular exosome; rough endoplasmic reticulum membrane; endoplasmic reticulum; endoplasmic reticulum membrane; extracellular matrix; Golgi apparatus
Genetic constraint (gnomAD): Loss-of-function variants: 21 observed, 25.01 expected, observed/expected ratio (o/e) 0.84, 90% interval 0.6 to 1.21. The upper end of that interval is the gene's LOEUF score, 1.21, which puts it in group 5 of 6, group 1 being the genes least tolerant of losing a copy. Missense variants: 303 observed, 315.07 expected, observed/expected ratio (o/e) 0.96, 90% interval 0.88 to 1.06. Synonymous variants: 109 observed, 109.48 expected, observed/expected ratio (o/e) 1, 90% interval 0.85 to 1.17.
Homologues: Orthologues: chimpanzee PLOD2 (99% identical), pig PLOD2 (95% identical), dog PLOD2 (94% identical), macaque PLOD2 (94% identical), rabbit PLOD2 (92% identical), mouse Plod2 (91% identical), rat Plod2 (91% identical), guinea pig PLOD2 (82% identical), tropical clawed frog plod2 (74% identical), zebrafish plod2 (69% identical), Drosophila melanogaster Plod (41% identical), Caenorhabditis elegans let-268 (40% identical). Paralogues in human: PLOD1 (58% identical), PLOD3 (57% identical), COLGALT2 (17% identical), COLGALT1 (16% identical), CERCAM (16% identical).
Diseases named in the same sentence as PLOD2 in open-access papers:
PLOD2 is named in the same sentence as 121 diseases in open-access papers, as found by Europe PMC text mining. Sharing a sentence is not in itself a finding about the gene and the disease. The quoted sentences say what the papers report.
breast carcinoma (59 papers, 2004 to 2025). "PLOD2, a key enzyme in collagen crosslinking, is associated with poor outcomes in oral squamous cell carcinoma, hepatocellular carcinoma, and breast cancer." (PMID 41142622, 2025). "For example, PAI-1 secreted by breast cancer cells activated PLOD2 in cancer-associated adipocytes (CAAs), facilitating the reorganisation of collagen into linear structures that promote cancer cell migration and metastasis." (PMID 39202782, 2024). "Accordingly, PLOD2, a well-known risk gene for breast cancer patients, as it stimulates EMT in cancer is triggered by hypoxia in both luminal cells and more abundantly in basal A cells in our study." (PMID 36826702, 2023). "Several studies found an association between PLOD2 overexpression and poor outcome in multiple types of cancer, such as sarcoma, breast cancer, hepatocellular carcinoma and bladder cancer." (PMID 35682709, 2022). "In breast cancer tumorigenesis, high expression of PLOD2 was positively associated with poorer prognosis." (PMID 33503035, 2021). "Of note, expression of just one of these basal B-specific splice variants, which are CTNND1, ENAH and PLOD2, is sufficient to lower the disease-specific survival rate of basal B-like breast cancer patients compared to basal A-like." (PMID 33845831, 2021). "Clinical samples were used to confirm that PLOD2 expression is increased in tumor tissue and is associated with poor prognosis of breast cancer patients." (PMID 30563531, 2018). "In this study, we investigate the function of PLOD2 in breast cancer and explore the underlying adipocyte-regulated mechanisms responsible for promoting PLOD2 expression." (PMID 30563531, 2018). "Another collagen-modifying enzyme, procollagen-lysine 2-oxyglutarate 5-dioxygenase 2 (PLOD2), was implicated in fibrillar collagen formation by breast cancer cells and as a result enhanced breast cancer cell metastasis to lymph nodes and lung." (PMID 30356678, 2018). "Loss-of-function studies indicated that PLOD2 knockdown suppressed cell migration and disrupted the formation of actin stress fibers in breast cancer cells and abrogated the migration induced by following coculture with adipocytes." (PMID 30563531, 2018). "The association of PLOD2 expression with poor prognosis was also significant in different subtypes of breast cancer, especially in basal-like tumors, which exists same characteristics with TNBC." (PMID 30563531, 2018). "Also, the higher expression of the PLOD1 and PLOD2 genes was found in hypoxic breast cancer cells and is associated with an increased risk of mortality." (PMID 38611696, 2024). "To further validate the epigenetic modulation potential of SKD and M.SssI, we stably integrated the ZF-SKD and ZF-M.SssI fusion genes into the genome of highly proliferating MDA-MB-231 breast cancer cells, in which high PLOD2 expression was shown to be associated with metastatic potential." (PMID 32455614, 2020). "Thus, PLOD2 mediated cancer-associated adipose caused structural changes of collagen to promote breast cancer metastasis." (PMID 31170987, 2019). "It was suggested that PLOD2 is critical for fibrillar collagen formation by breast cancer cells, increases tumor stiffness, and is required for metastasis to lymph nodes and lungs." (PMID 38611696, 2024). "Knockdown of P4HA1, P4HA2, and PLOD2 inhibits the spontaneous metastasis of breast cancer cells to the lungs and lymph nodes of mice." (PMID 37490147, 2023). "PLOD2 can enhance the development of a fibrous microenvironment and thus promote cell survival and pulmonary metastasis in breast cancer." (PMID 36632453, 2023). "Mechanistically, PAI-1 is secreted by breast cancer cells and promotes the expression of PLOD2 in adipocytes by activating the PI3K/AKT-FOXP1 axis." (PMID 36670988, 2023). "In an in situ mouse model of breast cancer, local tumor invasion and lung metastasis were impaired by knocking down PLOD2 in breast cancer cells." (PMID 38008826, 2023).
breast carcinoma (continued). "PLOD2 promotes breast cancer cell mesenchymal phenotypes and stemness through upregulating succinate." (PMID 38008826, 2023). "The knockdown of PLOD2 also impairs the invasion of breast cancer cells into the adjacent normal tissue of the mammary fat pad." (PMID 37490147, 2023). "The roles of PLOD2 in breast cancer, sarcoma, bladder cancer, and renal cell carcinoma were thoroughly discussed in a previous review." (PMID 35300417, 2022). "PLOD2 overexpressed in many cancers, including hepatocellular carcinoma, breast cancer, and sarcoma." (PMID 35154316, 2022). "PLOD2 plays a role in various cancers, such as renal clear cell carcinoma, laryngeal cancer, esophageal squamous cell carcinoma, breast cancer, osteosarcoma, liver cancer, and lung cancer." (PMID 35912206, 2022). "Upregulation of PLOD2 has been observed in various human malignancies, including breast cancer, biliary cancer, colorectal cancer, glioma, and liver cancer, as well as in CESC." (PMID 34258263, 2021). "In recent years, increasing research has revealed the pivotal role of PLOD2 in various cancer types, particularly in breast cancer, hepatocellular carcinoma, bladder cancer, sarcomas, and renal cell carcinoma." (PMID 35141213, 2021). "To date, several types such as lung cancer, breast cancer, colorectal cancer had revealed highly expressed PLOD2 with a poor prognosis." (PMID 34565301, 2021). "For instance, hypoxia-induced factor-1 activates PLOD1 in breast cancer, and to a great extent, activates PLOD2 in cancer development." (PMID 34646265, 2021). "In other solid tumors, such as hepatocellular carcinoma and breast cancer, high expression of PLOD2 is also reported to be significantly related to the decrease of DFS." (PMID 34944486, 2021). "Overexpression of PLOD2 has been observed in laryngeal squamous cell carcinoma, biliary tract cancer, hepatocellular carcinoma, breast cancer, bladder cancer, sarcoma, oral carcinoma, and renal cell carcinoma and is closely related to a poor prognosis." (PMID 32258155, 2020). "PLOD2 deregulation has been described in sarcoma, breast cancer, glioma, lung cancer, and cervical cancer." (PMID 32033341, 2020). "Based on other reports using this system, these data seem to indicate that SKD and M.SssI-induced repression of PLOD2 is sustained in these highly proliferative breast cancer cells." (PMID 32455614, 2020). "Immunoblot assay further confirmed that different breast cancer cells dramatically induced PLOD2 expression in adipocytes, while exerted little effect on LOX protein expression." (PMID 31170987, 2019). "Collectively, our results inferred that PLOD2 inhibitor attenuated breast cancer metastasis, at least in part through hampering the collagen structural." (PMID 31170987, 2019). "It has been reported that adipocyte-derived IL-6 promoted the up-regulation of PLOD2 in breast cancer cells via activating JAK/STAT3 and PI3K/AKT pathways." (PMID 31170987, 2019). "(B) qPCR analysis of PLOD2 expression in adipocytes cultured alone or with breast cancer cells (MDA-MB-231 or SKBR-3) for 72 h." (PMID 31170987, 2019). "Hypoxia-inducible factor-1α also regulates PLOD1 transcription in breast cancer; however, PLOD2 activity is more critical for HIF-1-induced cancer progression." (PMID 30770789, 2019). "We are the first to report that CAAs remodels collagen alignment in a PLOD2 dependent manner during crosstalk with breast cancer cells in vitro and in vivo, which further promotes breast cancer metastasis." (PMID 31170987, 2019). "The overexpression of PLOD2 is closely related to a poor prognosis in lung cancer and breast cancer, based on the Kaplan-Meier analysis." (PMID 31455288, 2019). "In breast cancer, PLOD2 was activated in breast cancer cells upon coculturing with adipocytes, while the knockdown of PLOD2 in cancer cells blocked the migration capacity stimulated by adipocytes." (PMID 31170987, 2019).
breast carcinoma (continued). "adipocyte-derived collagen reorganization, inhibition of PLOD2 abrogated the linearly collagen deposited by CAAs, which further inhibited breast cancer metastasis." (PMID 31170987, 2019). "Consistently, cocultured with breast cancer cells led to a dramatical upregulation of PLOD2 expression in human ASC adipocytes." (PMID 31170987, 2019). "Activation of PLOD1 and PLOD2 at the transcription level by HIF-1 is required for biogenesis of collagen in breast cancer cells." (PMID 31308057, 2019). "Knockdown of PAI-1 in breast cancer cells reversed the PLOD2 activation in CAAs, which subsequently inhibit breast cancer metastasis induced by adipose tissue in vivo." (PMID 31170987, 2019). "Consistent with this, knockdown of PLOD2 expression in a breast cancer cell line reduced collagen deposition in the primary tumor and reduced tumor growth in a mouse model." (PMID 31446433, 2019). "Further, we showed the secretion of PAI-1 by breast cancer cells exerted a key role in activating PLOD2 in CAAs through the PI3K/AKT-FOXP1 pathway." (PMID 31170987, 2019). "PLOD2 was found to be overexpressed in bladder cancer, oral carcinoma, hepatocellular carcinoma, breast cancer, sarcoma, and renal cell carcinoma and was closely related to a poor prognosis." (PMID 31455288, 2019). "Several studies have suggested that PLOD2 is correlated with poor prognosis of multiple cancers, including sarcoma, lung cancer, renal cell carcinoma, breast cancer, cervical cancer and bladder cancer." (PMID 31170987, 2019). "Next, lentivirus-mediated loss-of-function experiments were used to explore the function of lysyl hydroxylase (PLOD2) in breast cancer migration and adipocyte-dependent migration of breast cancer cells." (PMID 30563531, 2018). "In this study, we confirmed that PLOD2 mediates adipocyte-stimulated breast cancer metastasis and promotes the epithelial-mesenchymal transition (EMT) of breast cancer cells, suggesting that PLOD2 directly regulates breast cancer metastasis." (PMID 30563531, 2018). "Taken together, these findings provide new insights into the connections between adipokines and PLOD2 in breast cancer and support a crucial role for PLOD2 in human breast cancer metastasis." (PMID 30563531, 2018). "Over the last several years, PLOD2 deregulation has been observed in sarcoma, breast cancer, glioma, lung cancer and cervical cancer." (PMID 30563531, 2018). "Although HIF-1 induces expression of PLOD1 and PLOD2, PLOD2 expression in breast cancer cells is more important for fibrillary collagen formation, tumor stiffness and cancer metastasis to lymph nodes and lungs." (PMID 30003082, 2018). "Several studies have suggested that PLOD2 is dysfunctional in multiple cancer types, including sarcoma, lung cancer, breast cancer, glioblastoma, cervical cancer and bladder cancer." (PMID 30563531, 2018). "The significance of PLOD2 expression in breast cancer was further confirmed by immunohistochemistry in a tumor tissue microarray." (PMID 30563531, 2018). "This study provides novel evidence that adipocytes promote breast cancer metastasis via activation of PLOD2." (PMID 30563531, 2018). "The PLOD2 expression level is significantly upregulated in breast cancer compared to normal mammary tissue, and the upregulation correlates with short disease-related survival." (PMID 30003082, 2018). "Further investigation revealed that adipocyte-derived IL-6 and leptin promote PLOD2 expression, thus facilitating breast cancer metastasis." (PMID 30563531, 2018). "b Real-time PCR analysis (up) and Western blotting analysis (down) determining the expression of PLOD2 in several breast cancer cell lines." (PMID 30563531, 2018). "PLOD2 was positively correlated with the stage of breast cancer, respectively, strongly expressed in breast cancer at stage II and III." (PMID 30563531, 2018).
breast carcinoma (continued). "To investigate the role of PLOD2 during adipocyte-dependent migration and metastasis of breast cancer cells in vitro, we examined the effects of PLOD2 knockdown in MDA-MB-231 cells on migration, invasion, EMT and actin stress fiber formation." (PMID 30563531, 2018). "Here, we show that PLOD2 is upregulated in breast cancer cells during adipocyte-driven migration and invasion." (PMID 30563531, 2018). "We observed that treatment with recombinant human leptin resulted in a significant increase in PLOD2 expression in breast cancer cells in a time-dependent manner." (PMID 30563531, 2018). "Together, our results suggest that pharmacological inhibition of IL-6 and leptin as well as the downstream JAK/STAT3 and PI3K/AKT signaling pathways can decrease PLOD2 expression and suppress breast cancer metastasis." (PMID 30563531, 2018). "Gene expression profiling and Western blotting analyses revealed that PLOD2 was upregulated in breast cancer cells following coculture with adipocytes; this process was accompanied by enhanced breast cancer cell migration and invasion." (PMID 30563531, 2018). "Function of PLOD2 in lung cancer progression differs slightly from breast cancer; ectopic expression of PLOD2 enhances both primary cancer growth and metastasis." (PMID 30003082, 2018). "The role of PLOD2 in breast cancer metastasis was further confirmed using orthotopic mammary fat pad xenografts in vivo." (PMID 30563531, 2018). "It has been reported that PLOD2 is required for metastasis to lymph nodes and lungs in breast cancer." (PMID 28410212, 2017). "PLOD2 mediated collagen cross-linking has also been shown to further promote the development of a fibrotic microenvironment that enhanced breast cancer cell survival and facilitated metastasis to the lung and lymph nodes." (PMID 28423580, 2017). "The long-established hypoxia-induced gene PLOD2 is histologically over-expressed in sarcoma, glioblastoma, breast cancer and hepatocellular carcinoma, and it is an independent prognostic factor in glioblastoma and hepatocellular carcinoma." (PMID 28507454, 2017). "Gilkes, D. M. and his colleagues have reported that PLOD2 is essential for hypoxia-induced breast cancer metastasis." (PMID 28410212, 2017). "As previously reported, PLOD2 expression strongly correlates with metastasis in several types of cancer, such as sarcoma, breast cancer and lung cancer." (PMID 28507454, 2017). "For breast cancer, these genes included PLOD2 (procollagen lysyl hydroxylase 2, recently reported to be essential for hypoxia-induced breast cancer metastasis), and LDHA, a key enzyme in the terminal end of glycolysis." (PMID 25961905, 2015). "Similarly, SRSF2 has been demonstrated to influence the malignant growth of human breast cancer by controlling the alternative splicing of PLOD2." (PMID 40129567, 2025). "Further, RASSF1C up-regulation of P4HA2 and PLOD2 expression was confirmed in vivo in lung cancer tissue developed in an orthotopic mouse model and in breast subcutaneous tumor tissue derived from breast cancer cells overexpressing RASSF1C or RASSF1A." (PMID 36826019, 2023). "Moreover, IL-6 or leptin can increase procollagen-lysine, 2-oxoglutarate 5-dioxygenase 2 (PLOD2) expression in breast cancer cells through the activation of the JAK/STAT3 and the AKT signalling pathway." (PMID 32033341, 2020). "Inhibition of PLOD2 in breast cancer cells could obviously reduce the collagen accumulation and distance metastasis." (PMID 33134376, 2020). "In addition, collagen reorganization at the tumor-adipose periphery, as well as the positive relevance between PAI-1 and PLOD2 in invasive breast carcinoma were confirmed in clinical specimens of breast cancer." (PMID 31170987, 2019).